ATP7B (ATPase copper transporting beta)
Diseases named in the same sentence as ATP7B in open-access papers (continued):
Sharing a sentence is not in itself a finding about the gene and the disease.
Menkes disease (25 papers, 2011 to 2025). A usually severe multisystemic disorder of copper metabolism, characterized by progressive neurodegeneration and marked connective tissue anomalies as well as typical sparse abnormal steely hair. "WD and Menkes’ disease (MD) are typically associated with abnormally elevated or decreased copper levels resulting from ATP7A- or ATP7B-related dysfunction, respectively." (PMID 40809021, 2025). "Loss-of-function mutations in copper transporters, such as ATP7A and ATP7B, lead to hereditary diseases, Menkes disease (MD), or WD." (PMID 28197076, 2017). "Mutations in ATP7A are associated with Menkes disease (MD), while ATP7B mutations cause Wilson's disease (WD)." (PMID 24904274, 2014). "In this study, we characterized 101 WD-causing ATP7B variants by testing whether variants were expressed and capable of Cu transport using Menkes disease fibroblast cells (YST), which lack Cu export and accumulate Cu." (PMID 40661833, 2025). "Their deficiency due to gene mutations is at the basis of WD (mutations of the ATP7B gene) and Menke’s disease (mutated ATP7A gene), two disorders characterized by severe neuropathological deficits and by neuropsychiatric symptoms in a high percentage of patients who are affected." (PMID 38928192, 2024). "Consistent with their important roles in maintaining health, mutations in ATP7A and ATP7B cause inherited disorders of Cu metabolism, which have been recognized as Menkes disease (MD) and Wilson’s disease (WD), respectively." (PMID 36414625, 2022). "Menkes disease (MD) and WD are genetic disorders associated with copper metabolism, characterized by mutations in the ATP7A or ATP7B genes, respectively." (PMID 40808953, 2025). "The mutation of the same residue in paralogous ATP7A causes Menkes disease, the pathogenic effect most probably associated with the disruption of the phosphotransfer reaction that is common for both ATP7A and ATP7B." (PMID 40661833, 2025). "Excess copper is removed from the cell by the ATP-driven copper transporters ATP7A and ATP7B, protecting cells from ROS, and defects can lead to copper storage diseases like Menkes disease." (PMID 38263136, 2024). "Menkes’ disease (MD) and Wilson’s disease (WD) are two major copper (Cu) metabolism-related disorders caused by mutations of the ATP7A and ATP7B ATPase gene, respectively." (PMID 38136617, 2023). "Similar to ATP7B, ATP7A is also involved in the copper death process, and the related diseases it affects have three manifestations: Menkes disease (MNK), occipital horn syndrome (OHS) and X‐linked distal spinal muscular atrophy 3 (SMAX3)." (PMID 39936900, 2025). "Failure in the cuprostatic network results in a variety of pathologies—including Menkes disease (MD), occipital horn syndrome, and Wilson's disease (WD), caused by mutations in the Cu+-P-type ATPases ATP7A and ATP7B." (PMID 39375833, 2024). "Dysregulation of copper metabolism leads to various diseases, exemplified by Menkes disease (MD) and Wilson’s disease (WD) which are caused by loss-of-function mutations in the copper transporter ATP7A or ATP7B, respectively." (PMID 39290994, 2024). "MEDNIK syndrome is caused by a pathogenic variant in the AP-1 sigma (σ) subunit, and shares multiple symptoms and cellular phenotypes with Wilson and Menkes disease, hence indicating the possible involvement of AP-1 in regulation of ATP7A and ATP7B." (PMID 38032054, 2024). "Analysis of Cu-transport by this and other mutants was monitored in Menkes disease fibroblast (YST) cells, which lack active ATP7A and ATP7B." (PMID 32778786, 2020).
ovarian carcinoma (25 papers, 2004 to 2025). A malignant neoplasm originating from the surface ovarian epithelium. "These transporters are observed to be upregulated in cisplatin-resistant cancer cells and high levels of ATP7A and ATP7B are associated with significantly poorer overall survival in patients with ovarian cancer and ovarian carcinoma, respectively." (PMID 39124859, 2024). "In a patient-derived gene expression profile, ATP7B has also been associated as a chemoresistance marker in ovarian carcinomas treated with cisplatin." (PMID 28008141, 2017). "Two studied variants of copper transporter ATP7B showed opposite effects on the ovarian cancer risk." (PMID 25591549, 2015). "The analyses showed also the importance of ATP7B gene in ovarian carcinogenesis, both studied variants of which significantly modulated the ovarian cancer risk in all groups excluding the group with BRCA1 mutation." (PMID 25591549, 2015). "For this purpose, localisation of ATP7A and ATP7B in A2780 human ovarian carcinoma cells and their cisplatin-resistant variant, A2780cis, was investigated." (PMID 18565219, 2008). "Tetrathiomolybdate, a copper chelator, inhibits ATP7B activity in ovarian cancer models, restoring cisplatin sensitivity by blocking drug export." (PMID 40406488, 2025). "ATP7B contributes to platinum resistance by actively exporting cisplatin and carboplatin out of ovarian cancer cells." (PMID 40406488, 2025). "APT7A and ATP7B have also been reported as predictive markers of platinum resistance in ovarian cancer." (PMID 37007145, 2023). "ATP7B is highly expressed in many tumours including BC, ovarian cancer, oesophageal cancer, gastric cancer, and hepatocellular carcinoma." (PMID 38259456, 2023). "For the association between copper metabolism-related cell death and drug sensitivity, ATP7B has been reported to mediate the drug resistance of platinum in cancers, such as ovarian cancer and head and neck cancer." (PMID 36276096, 2022). "Using ChIP and functional Luciferase Assays, we confirmed that TFEB is able to directly transactivate ATP7B in the presence of Pt in resistant ovarian cancer cells." (PMID 35053335, 2022). "We found that the promoter region of ATP7B contains CLEAR binding sites, which are used by TFEB for Pt-dependent activation of ATP7B transcription in resistant ovarian cancer cells." (PMID 35053335, 2022). "The copper efflux transporters ATP7A and ATP7B mediate cisplatin efflux, and overexpression of ATP7A during platinum-based chemotherapy was associated with poor survival in ovarian cancer patients." (PMID 33437029, 2021). "Using a synthetic lethality screen, we identified and validated three hit drugs that significantly reduced ATP7B-mediated tolerance to cisplatin in ovarian cancer cells." (PMID 32155756, 2020). "Using this strategy, we identified FDA-approved drugs that overcome resistance to cisplatin in ovarian cancer cells and characterized several ATP7B-dependent/independent molecular mechanisms behind the drug impacts." (PMID 32155756, 2020). "RNAi-mediated suppression of ATP7B enhanced the sensitivity of resistant ovarian cancer cells to cisplatin and promoted the ability of cisplatin to reduce the growth of tumor engrafts in nude mice." (PMID 31540259, 2019). "By screening a library of FDA-approved drugs we found a few compounds that suppress ATP7B trafficking in Pt-resistant ovarian cancer cells and promote cisplatin toxicity." (PMID 31540259, 2019). "Studies on patients with lung and ovarian cancer have indicated that high expression levels of ATP7A are correlated with poor response to CDDP treatments and that of ATP7B have similar outcomes in patients with lung, oral, esophagus, and ovarian cancer." (PMID 31450627, 2019). "Three cisplatin-resistant human ovarian carcinoma cell lines exhibited increased expression of one or the other of ATP7A or ATP7B." (PMID 24278698, 2012).
ovarian carcinoma (continued). "Moreover, lung cancer patients who have higher ATP7A expression exhibit poorer responses to cisplatin-based chemotherapy, and ATP7B and ATP7A are associated with resistance to cisplatin-based drugs in breast and ovarian cancer." (PMID 38305803, 2024). "Moreover, the copper-transporting ATPases ATP7A and ATP7B have been shown to regulate drug resistance in ovarian cancer." (PMID 36950684, 2023). "Although ATP7B expression and trafficking provided a significant contribution to cisplatin tolerance in ovarian cancer cells tested, it is likely that other mechanisms are involved in Pt-resistance because cisplatin treatment usually causes complex and multifactorial cellular responses." (PMID 32155756, 2020). "To circumvent ATP7B-mediated Pt tolerance we employed a high-throughput screen (HTS) of an FDA/EMA-approved drug library to detect safe therapeutic molecules that promote cisplatin toxicity in the IGROV-CP20 ovarian carcinoma cells, whose resistance significantly relies on ATP7B." (PMID 32155756, 2020). "Here, using synthetic lethality screening, we detected and validated three FDA-approved drugs, Tranilast, Telmisartan, and Amphotericin B, which promote Pt-mediated death in ovarian cancer cells, whose resistance to cisplatin relies on ATP7B in a significant manner." (PMID 32155756, 2020). "The previous finding indicates that ATP7B may have a different role in hepatocytes as compared to other cells, including ovarian carcinoma cells and primary MNK fibroblasts, where overexpression of the transporter was shown to rescue from Cp toxicity." (PMID 29416650, 2018). "In addition to ATOX1, investigation of the potential of other copper transporters and chaperones in siRNA therapy of NSCLC and other cancers, such as ATP7B in ovarian cancer and ATP7A in neuroblastoma is warranted." (PMID 23624903, 2013). "Moreover, the therapeutic potential of ATP7B gene silencing for reversing platinum resistance was tested in vivo delivering ATP7B siRNA incorporated into neutral nanoliposomes into nude mice bearing tumors from the ovarian cancer cell line A2780-CP20." (PMID 24278698, 2012). "Moreover, clinical study indicated that ATP7B was a cisplatin-resistant marker in ovarian cancer." (PMID 29301278, 2018). "Recent data from Howell's lab demonstrated that two P-type of ATPases ATP7A and ATP7B are involved in cisplatin resistance in human ovarian carcinoma cells by modulating cellular pharmacology of cisplatin and other metals, suggesting that a sequestration and secretory system may exist." (PMID 15199393, 2004). "Kaplan-Meier plotter analysis showed that except for LIAS, PDHB, and ATP7B, the factors related to PDHB were significantly negatively correlated with the survival cycle of ovarian cancer patients." (PMID 36484005, 2022). "Our own findings suggest that inhibitor of TFEB nuclear translocation increases cisplatin toxicity in another ovarian cancer cell line A2780-CP20, whose resistance to Pt involves elevated ATP7B expression." (PMID 35053335, 2022). "To this end we evaluated the response to cisplatin of two well-known ovarian cancer cell lines, IGROV-CP20 and A2780-CP20, whose tolerance to Pt drugs has been reported to significantly rely on ATP7B." (PMID 32155756, 2020). "Since cisplatin transporters can mediate the resistance of ovarian cancer cells to cisplatin, the protein levels of MRP2, ATP7A, ATP7B, and CTR1 in ovarian cancer A2780/CP70 and OVCAR3 cells were evaluated by Western blot analysis." (PMID 29301278, 2018). "Using resistant ovarian cancer IGROV-CP20 cells, we found that TFEB directly binds to the predicted coordinated lysosomal expression and regulation (CLEAR) sites in the proximal promoter and first intron region of ATP7B upon Pt exposure." (PMID 35053335, 2022).
ovarian carcinoma (continued). "Resistance to platinum compounds has also been related to increased levels of copper pumps; indeed, it has been demonstrated that cisplatin-resistant ovarian cancer cell lines have acquired, in part, their resistance via an increased protein level of copper-transporting ATPases (ATP7A and ATP7B)." (PMID 28008141, 2017). "Also, ATP7B, a lysosomal protein that is induced by TFEB and mediates the cisplatin lysosomal sequestration in resistant ovarian cancer cells, was down-regulated in TFEB-silenced cells compared to wild-type cells, excluding that it was involved in cisplatin resistance upon TFEB silencing." (PMID 39107857, 2024). "Finally, we tested whether this TFEB suppression strategy is effective in another ovarian cancer A2780-CP20 cell line, whose resistance to cisplatin relies on ATP7B in a significant manner." (PMID 35053335, 2022). "Among CNV increasing genes, only DLD in ovarian cancer samples was higher than that in normal ovarian tissues, while the expression levels of DBT, PDHB, ATP7B, etc. with CNV deletion were not consistent with CNV changes." (PMID 36307842, 2022). "Finally, by analyzing a public gene expression dataset, the same authors found that ovarian cancer patients with elevated levels of hCtr1 in their tumors, but not ATP7A and ATP7B, had more favorable outcomes after treatment with platinating drugs than those expressing low hCtr1 levels." (PMID 24278698, 2012).
liver disease (17 papers, 2013 to 2025). "At early stages of liver disease that are associated with hepatocellular inflammation, both tx-j and Atp7b−/− B6 mice were characterized by changes in hepatic lipidomic profile and signs of altered PUFA metabolism." (PMID 38072238, 2024). "Wilson's disease (WD) is a monogenetic liver disease that is based on a mutation of the ATP7B gene and leads to a functional deterioration in copper (Cu) excretion in the liver." (PMID 32997714, 2020). "Compound heterozygous ATP7B mutations (p.Gly837X/p.Pro992Leu) were found in an 18-year WD female (M1031, II:1) presented with liver disease at the onset age of 2 years old, the earliest reported onset age." (PMID 23843956, 2013). "The c.2333G>T(p.R778L) variant in the ATP7B gene is the most prevalent pathogenic variant among Asian patients with WD, and those patients carrying this variant predominantly present with early liver disease and low serum ceruloplasmin." (PMID 40104154, 2025). "The new ATP7B deletion variant c.1448_1455del was identified in case 7, which had liver disorders." (PMID 33879678, 2021). "A total of 140 pediatric individuals had molecular testing for ATP7B variants between 2010 and 2015, due to liver disease of unknown etiology or suspicion of WD due to family history." (PMID 32154060, 2020). "ATP7B gene mutations lead to ATP7B protein dysfunction, which in turn causes accumulation of copper in the liver, brain, kidneys and corneas, with a wide range of clinical symptoms, including hepatic disorders, neuronal degeneration of the brain, and Kayser-Fleischer rings at the corneal limbus." (PMID 29649982, 2018). "To assess the extent of hepatic oxidative stress in early stages of liver disease in WD, we examined the hepatic lipidome in tx-j and Atp7b−/− B6 for changes in the arachidonic acid-derived marker of auto-oxidation, 9-HETE." (PMID 38072238, 2024). "Although ATP7B is expressed in the brain, copper overload appears to be dependent on liver disease, as it is potentially reversible with a liver transplant." (PMID 38928192, 2024). "With a cut-off of 18.5%, REC was able to discriminate WD patients from heterozygous ATP7B carriers, healthy controls and patients with other liver diseases." (PMID 36673066, 2023). "In Atp7b−/− mice, copper starts to accumulate in the liver during the first weeks of life, leading to overt liver disorder by 12–20 weeks of age." (PMID 36092366, 2022). "Sirius red staining, grading of necroinflammatory activity, and gene expression analysis of fibrosis and inflammation marker genes confirmed the correction of liver disease by int-ATP7B." (PMID 36092366, 2022). "Therefore, our newly established Atp7b KI mouse model provides an optimal tool to explore pathological mechanisms of Cu homeostasis and monitor therapeutic responses and drug-related liver disease in pilot studies for WD." (PMID 40104154, 2025). "Therefore, the Atp7b−/− B6 model can be used to study compensatory regulatory mechanisms and metabolic changes in the state of liver disease related to copper toxicity." (PMID 38072238, 2024). "In the present work, we evaluated whether full-length ATP7B in hepatocytes can be reconstituted by split intein technology and its efficacy in restoring copper homeostasis and prevention of liver disease of a WD mouse model." (PMID 36092366, 2022). "In global Atp7b knockouts, the loss of building blocks necessary for NADPH and glutathione synthesis (nucleotides and amino acids- see altered pathways) compromises this protective compensatory response causing the onset of liver disease." (PMID 33707579, 2021). "We here report on the diagnosis of a boy who has a novel compound heterozygote ATP7B mutation, no family history of WD, and subtle neuropsychiatric symptoms without hepatic disease." (PMID 29761093, 2018).
liver disease (continued). "Several studies have documented similar discrepancies, where patients with the same ATP7B mutation may present with either severe hepatic disease or neurological symptoms, or both, without a clear genetic explanation for the differential phenotype expression." (PMID 41225982, 2025). "ATP7B, SLC25A13, and G6PC were the top three genes related to monogenic liver disease in this study." (PMID 33763395, 2021).